PINK1 (PTEN induced kinase 1)
Diseases named in the same sentence as PINK1 in open-access papers (continued):
Sharing a sentence is not in itself a finding about the gene and the disease.
glioma (13 papers, 2018 to 2026). A benign or malignant brain and spinal cord tumor that arises from glial cells (astrocytes, oligodendrocytes, ependymal cells). "An experimental study revealed that the loss of PINK1 resulted in increased proliferation of glioma cells, reduced oxygen consumption, and increased glycolysis." (PMID 33066407, 2020). "Meanwhile, gliomas characterized by downregulated expression ofthe protective PINK1 gene correlate with low survival time ofpatients who have undergone chemotherapy or radiation therapy." (PMID 39539523, 2024). "Subsequent mechanistic studies indicated that FAM72A promoted glioma progression by regulating mitophagy through the Pink1/Parkin signaling pathway." (PMID 37151394, 2023). "Mechanistically, we found that FAM72A promoted glioma progression by regulating mitophagy through the Pink1/Parkin signaling pathway." (PMID 37151394, 2023). "By contrast, PINK1 re-expression inhibited ROS, glioma cell growth, and oxygen glycolysis." (PMID 33066407, 2020). "The AKT arm of this pathway is consistent with what has been described in glioma stem cells and Drosophila neuroblasts, whereby Notch1 associates with PTEN-induced kinase 1 (PINK1) on the mitochondrial surface to modulate mitochondrial function, and activates mTORC2/AKT signaling." (PMID 30564555, 2018). "Additionally, changes in the expression profiles of PINK1 and GPR55 were observed in correlation with survival rates in high-grade vs. low-grade gliomas, suggesting potential alterations in inflammatory and metabolic profiles." (PMID 40565152, 2025). "Therefore, as the malignancy level of glioma cells increases, the elevated levels of DNM1L/DRP1 and FIS1 lead to heightened expression of PINK1/PARKIN, promoting mitochondrial fission and reshaping MRC through autophagy." (PMID 39350223, 2024). "However, neither FAM72A nor its function in glioma has yet been reported, and whether FAM72A contributes to tumor progression through Pink1/Parkin signaling remains unknown." (PMID 37151394, 2023).
Hepatic steatosis (13 papers, 2020 to 2026). Steatosis is a term used to denote lipid accumulation within hepatocytes. "Our findings reveal that RES ameliorates fatty liver injury primarily by inhibiting the NLRP3 inflammasome through PINK1-mediated mitophagy, which provides a potential novel therapeutic strategy for mitigating fatty liver disease." (PMID 41976001, 2026). "Collectively, these findings indicate that lipotoxic environment would influence the expressions of Mertk and PINK1, highlighting their potential role in hepatic steatosis and metabolic stress." (PMID 40964873, 2025). "Mechanistic studies have revealed that cyanidin-3-O-glucoside (C3G) improves hepatic steatosis and glucose metabolism by upregulating the expression and mitochondrial localisation of PINK1 and Parkin, thereby promoting PINK1-mediated mitophagy." (PMID 40906106, 2025). "For instance, quercetin reduced hepatic steatosis by inducing mitophagy through the Pink1/Parkin signaling pathway, thereby protecting NAFLD." (PMID 35889739, 2022). "This study aimed to determine the effect of corn peptides on hepatic steatosis both in vivo and in vitro and to further investigate whether they promoted hepatocyte autophagy by activating the PINK1–Parkin pathway to attenuate NAFLD." (PMID 37808204, 2023). "Moreover, the induction of hepatic steatosis in rats by ethanol was demonstrated to dramatically activate mitophagy by elevating PINK1 expression on mitochondria to eliminate damaged mitochondria." (PMID 32235615, 2020). "In addition, ethanol-activated PINK1-dependent mitophagy was shown to be strongly correlated with the mitochondrial expression of Parkin and the level of the indicator of oxidative mtDNA damage, 8-OHdG, in the rat model of ethanol-induced hepatic steatosis." (PMID 32235615, 2020). "CP can significantly upregulate the protein expression of PGC-1α, PPARα, PINK1, Parkin, ATG7, and LC3I/II in the liver of high-fat dilated-induced NAFLD rats, downregulate that of P62, activate mitophagy mediated by PINK1/Parkin, and block liver steatosis induced by high-fat diet in rats." (PMID 38348222, 2024). "Inhibition of Parkin- and PTEN-induced putative kinase 1 (PINK1)-mediated mitophagy exacerbates hepatic lipogenesis, inflammation, and insulin resistance in NAFLD mice, and upregulation of mitophagy levels effectively ameliorates hepatic steatosis in NAFLD mice." (PMID 38348222, 2024). "The results, showing the involvement of PINK1 and PARKIN in the coordination of the mitophagic flux, strengthen the notion that mitophagy may play an important and a protective role against the pathogenesis of hepatic steatosis." (PMID 35205361, 2022).
Insulin resistance (13 papers, 2014 to 2025). Increased resistance towards insulin, that is, diminished effectiveness of insulin in reducing blood glucose levels. "Induction of insulin resistance in vitro by the key genetic Alzheimer risk factor apolipoprotein E4 retains Pink1 mRNA at the mitochondria and prevents proper PINK1 activity, especially in neurites." (PMID 38504131, 2024). "PTEN-induced kinase 1, a mitochondrial serine/threonine protein encoded by the PINK1 gene, alleviated insulin resistance by lowering the production of ROS mediated by the MAPK pathways." (PMID 37109219, 2023). "Finally, in vitro experiments verified that TAC-induced hepatic insulin resistance was associated with PINK1, which requires in vivo verification." (PMID 37151651, 2023). "PINK1 can mitigate palmitoyl-cysteine-induced insulin resistance in hepatocytes by suppressing ROS-mediated MAPK signaling pathways." (PMID 41299664, 2025). "In the skeletal muscle of mice with diet-induced insulin resistance, UA has been shown to increase PINK1/PRKN (Parkin) mitophagy pathways." (PMID 41374004, 2025). "The knockdown of Drp1 inhibits the activating effect of CK on skeletal muscle mitochondria, suggesting that CK activates Drp1/PINK1-mediated mitophagy, which in turn improves the mitochondrial quality and function and alleviates insulin resistance." (PMID 38348222, 2024). "Disruption of insulin signalling by ApoE4 leads to impaired PINK1 activation in cultured neurons and therefore suggests a mechanistic connection between the frequently observed neurodegenerative phenotypes of insulin resistance and mitochondrial dysfunction." (PMID 38504131, 2024). "Together, these data suggest that dysregulation of insulin- and AMPK-mediated Pink1 mRNA localization and PINK1 activity are contributing to mitochondrial dysfunction under pathological conditions modelling insulin resistance in vitro." (PMID 38504131, 2024). "The results indicated that knocking down PINK1 in hepatic cells reversed the insulin resistance induced by TAC through upregulating the expression of GLUT2 and IRS2/AKT." (PMID 37151651, 2023). "In conclusion, our findings showed that in mice, TAC significantly affected the glucose homeostasis of the liver via the PINK1/Parkin pathway and induced hepatic insulin resistance." (PMID 37151651, 2023). "siRNA-mediated knockdown of PRKN and PINK1 abrogated the TAC-induced reduction in hepatic insulin resistance." (PMID 37151651, 2023). "As a mitophagy mediator, PTEN-induced putative kinase 1 (PINK1) expression was decreased under insulin resistance conditions." (PMID 33339212, 2020). "However, as insulin resistance progresses from prediabetes to T2D, muscle biopsies have shown downregulation of PINK1‐PARKIN alongside mitochondrial dysfunction." (PMID 41214862, 2025). "This suggests that during the process of insulin resistance, mitochondrial dysfunction may lead to a weakened interaction between PINK1 and Parkin proteins." (PMID 39761309, 2025). "In summary, insulin resistance is associated with a decrease in Parkin protein levels, while PINK1 protein shows no significant changes." (PMID 39761309, 2025). "Herein, we found that TAC-induced PINK1 accumulation led to hepatic insulin resistance, which might be regulated through mitophagy-related signaling pathways." (PMID 37151651, 2023). "However, we cannot exclude the possibility that the reduction in PINK1 levels, through inducing increased levels of basal insulin secretion, could contribute to the development of insulin resistance over time." (PMID 24806840, 2014). "Knockdown of hepatic PINK1 regulated downstream molecules of the PINK1/Parkin pathway (GLUT2 and IRS2), which reversed TAC-induced insulin resistance." (PMID 37151651, 2023). "Initially, TAC was observed to induce hepatic insulin resistance, impair IRS2/AKT signaling, and upregulate PINK1/Parkin in mice." (PMID 37151651, 2023).
Insulin resistance (continued). "In vitro, CK activates PINK1/Parkin-mediated mitophagy in insulin-resistant cellular models established by FA and HG-treated mouse adult myoblasts (C2C12), promotes mitochondrial fission/fusion stabilization, and ameliorates FA-induced insulin resistance in skeletal muscle cells." (PMID 38348222, 2024).
Stroke (13 papers, 2017 to 2026). Sudden impairment of blood flow to a part of the brain due to occlusion or rupture of an artery to the brain. "Numerous studies have shown that the PINK1/Parkin-mediated autophagy pathway is integral to the pathogenesis of various disorders, including stroke, neurodegenerative diseases, and multiple sclerosis." (PMID 41540456, 2026). "Accumulated evidence suggests that PINK1/Parkin-mediated autophagy is involved in the pathogenesis of various diseases, including stroke, neurodegenerative disorders, and multiple sclerosis." (PMID 41540456, 2026). "In recent years, there has been more and more studies on this mechanism, which to some extent shows that UPS plays an important role in PINK1/Parkin pathway in the process of brain injury in stroke." (PMID 35462700, 2022). "In the stroke induced by mitochondrial dysfunction, PINK1/Parkin pathway mediates ubiquitination of dysfunctional mitochondrial OMM protein, and then clears abnormal mitochondria through crosstalk with autophagy." (PMID 35462700, 2022). "In recent years, there has been an increase in the research on this mechanism in stroke, which illustrates to some extent that the PINK1-Parkin pathway is involved in the process of brain injury in stroke." (PMID 34335233, 2021). "Notably, Tug1 mitigates post-stroke microglial pyroptosis by promoting PINK1/Parkin-dependent mitophagy." (PMID 41007413, 2025). "Similarly, nanocarrier systems such as PINK1 siRNA-loaded PLGA nanoparticles have achieved microglia-targeted delivery in rodent photothrombotic stroke, reducing excessive mitophagy, infarct volume, and improving functional outcomes." (PMID 41007413, 2025). "Therefore, DHA can protect against neuronal apoptosis after stroke by clearing the damaged mitochondria through Pink1/Parkin-mediated mitophagy and by alleviating mitochondrial dysfunction." (PMID 36254232, 2022). "Investigation of the role of the PINK1/Parkin pathway in mammalian neurons is necessary, since mitophagy disturbance involved with the PINK1/Parkin pathway might be a prerequisite of stroke therapeutic research." (PMID 30501621, 2018). "Furthermore, recent studies showed that the chronic neurodegeneration-related proteins including α-Syn, DJ-1, Parkin and PINK1 are also involved in the neuronal death following acute insults like a stroke." (PMID 28273718, 2017). "In a photothrombotic stroke model, AP39 decreased infarct volume and promoted mitophagy via activation of the PINK1/Parkin pathway, showing sex-dependent effects." (PMID 41465271, 2025). "Single-cell and spatial transcriptomics in human post-stroke tissue remain scarce, but preliminary analyses suggest that increased expression of autophagy-related genes such as ATG5 and PINK1 in microglial-enriched clusters correlates with larger infarct volumes and worse recovery outcomes." (PMID 41007413, 2025). "Therefore, it is necessary to pay attention to the role of PINK1/Parkin/UPS mechanism in mitochondrial damage after stroke, rather than autophagy." (PMID 35462700, 2022).
cardiomyopathy (12 papers, 2015 to 2026). A disease of the heart muscle or myocardium proper. "PINK1-dependent mitophagy has been linked to this reprogramming and mice expressing a cardiac specific mitofusin-2 mutation, which cannot be phosphorylated by PINK1, developed progressive cardiomyopathy and died by 7-8 weeks of age." (PMID 32420530, 2020). "HO-1 overexpression has shown to protect against doxorubicin-induced cardiomyopathy through induction of the PINK1 and Parkin expression, whereas HO-1 deficiency resulted in failure to upregulate PINK1 and Parkin-mediated mitophagy." (PMID 30333475, 2018). "One of the main pathologic processes associated with Parkinson’s disease and cardiomyopathy is functional disorder of PTEN-inducible kinase 1 (PINK1), Parkin, which mediates mitophagic elimination of damaged or senescent mitochondria." (PMID 27904993, 2017). "The inhibition of PINK1/Parkin-mediated mitophagy in HFD-induced cardiomyopathy is primarily regulated by BRD4 and ACC2, suggesting potential therapeutic targets to modulate mitophagy and mitigate disease progression." (PMID 40004130, 2025). "Ablation of ALCAT1 dramatically increased expression of PINK1, which supports a protective function of PINK1 against oxidative stress and cardiomyopathy." (PMID 26481155, 2015). "However, the role of PINK1/Parkin-mediated mitophagy in DOX-induced cardiomyopathy is still in dispute." (PMID 34977042, 2021). "Second, EDC exposure alters mRNAs and proteins involved in ceRNA networks, activating the PTEN-induced kinase 1/Parkin and transforming growth factor-β1/LIM domain kinase 1 signaling pathways, leading to cardiomyopathy." (PMID 41765384, 2026). "Interestingly, and unlike cardiomyocytes of rodent models lacking Pink1 or Parkin, which show accumulation of morphologically abnormal mitochondria and heart pathology, patients with MMA rarely display cardiomyopathy." (PMID 36231140, 2022). "Interestingly, and unlike cardiomyocytes of rodents lacking Pink1 or Parkin, which display accumulation of morphologically abnormal mitochondria and heart pathology, patients with MMA rarely manifest symptoms of cardiomyopathy." (PMID 34524466, 2021).
injury (12 papers, 2020 to 2025). Damage inflicted on the body as the direct or indirect result of an external force, with or without disruption of structural continuity. "In vitro, NVs protected against radiation-induced skin injury by reducing apoptosis, promoting DNA repair, and regulating PINK1/Parkin-mediated mitophagy." (PMID 41142427, 2025). "Comprehensively, considering the mitophagy-mediated dysfunction mitochondrial clearance inhibits hepatic I/R injury, activating the PINK1/Parkin pathway is a potential strategy in the treatment of ischemia hepatic injury." (PMID 36506934, 2022). "A recent study showed that besides the antiapoptotic function of Bcl2, its overexpression inhibits mitophagy via modulating the PINK1/Parkin pathway in a model of acute lung injury." (PMID 35814769, 2022). "Our in vitro results lead us to propose PINK1-mediated mitophagy with mtDNA release as a therapeutic target via TLR9/MyD88 signaling in mechanical stretching-induced acute lung injury." (PMID 33015037, 2020). "Therefore, we concluded that the PINK1/Parkin-pathway via AMPK might play an important role in Cr-induced liver injury and can be used as a potential target for the treatment of Cr-induced liver injury." (PMID 39099653, 2024). "In a septic kidney injury model, MIF inhibits mitophagy by disrupting the PINK1-Parkin interaction." (PMID 41357167, 2025).
intestinal infection (12 papers, 2020 to 2025). "Our previous work showed that repeated intestinal infection with C. rodentium in mice harboring a mutation in PD-related gene (Pink1−/−) triggered the development of PD-relevant dopamine-sensitive motor symptoms later in life." (PMID 40883285, 2025). "A recent study in PTEN-induced kinase-1 (Pink1)-deficient mice, a model of PD based on deficiency of Pink-1, a mutated protein associated with autosomal recessive parkinson, has shown that PD-like symptoms can be developed after gastrointestinal infections in mice." (PMID 33801153, 2021). "Moreover, a study conducted in mice has corroborated that intestinal infection triggers dopaminergic cell loss and motor impairment in a Pink1 knockout model of PD38." (PMID 34408160, 2021). "We previously developed a model system in PINK1 KO mice displaying PD-like motor symptoms at late stages following intestinal infections." (PMID 40404738, 2025). "We find that intestinal infection in PINK1 KO mice induces early immune dysregulation in the colon marked by the promotion of proinflammatory myeloid cell differentiation with an increased capacity to promote T-cell cytotoxic profiles." (PMID 40404738, 2025). ", we determined transcriptional regulation driven by PINK1 in specific immune cell types in response to intestinal infection." (PMID 40404738, 2025). "Our findings collectively suggest that effector CD8 + T cells are expanding in the gut of PINK1 KO mice at an early stage after intestinal infection, and it is likely that these T cells induce pronounced cytotoxic outcomes." (PMID 40404738, 2025). "In Pink1−/− mice, intestinal infection with Citrobacter rodentium resulted in degeneration of dopaminergic axons in the striatum and motor dysfunction." (PMID 38750146, 2024). "Taken together, these data support the role of PINK1 as a suppressor of the immune system, highlighting the connection between intestinal infection and immunity as key players in the pathophysiology of PD." (PMID 35408836, 2022). "More recently, it was shown that intestinal infection/dysfunction in PINK1-KO mice and PINK1-mutant flies also leads to neuroinflammation and neurotoxicity [27•, 86]." (PMID 35674870, 2022). "This was further validated in a recent study, where an intestinal infection in PINK1 knockout mice (PINK1-/-) induced mitochondrial antigen presentation and the establishment of mitochondrial-specific CD8+ T cells." (PMID 33291304, 2020). "This hypothesis was further confirmed in an in vivo study, in which an intestinal infection with Gram-bacteria of PINK1 knock-out mice engaged MitAP and mitochondria-specific cytotoxic T-cells in the periphery and the brain." (PMID 35408836, 2022). "Furthermore, these findings are in line with previous research, which provided evidence that intestinal infection in PINK1-/- mice elicits the recruitment of cytotoxic CD8+ T-cells in the periphery and in the brain, triggering PD-like symptoms." (PMID 36466826, 2022). "Intestinal infection with Gram-negative bacteria in PINK1 knockout mice elicits the establishment of cytotoxic CD8 T-cells in the periphery and the brain, highlighting the relevance of the gut–brain axis in the PD." (PMID 38069088, 2023). "Another study has recently reported that intestinal infection with Gram-negative bacteria in Pink1-/- mice acts as a triggering event in PD." (PMID 33532138, 2021). "Furthermore, intestinal infection with Gram-negative bacteria triggers PD-like symptoms in PINK1 knockout mice, leading to the development of cytotoxic mitochondria-specific T-cells in both the periphery and the brain." (PMID 38069088, 2023). "Recent work has demonstrated that an autoimmune response in the absence of PINK1 could participate in the etiology of PD following intestinal infection with Gram-negative bacteria in PINK1-/- mice, through mitochondrial specific CD8+ T- cells capable of killing dopaminergic neurons in vitro." (PMID 36466826, 2022).